ZNF788P (zinc finger family member 788, pseudogene)
Synonyms: FLJ46419; formerly ZNF788
Gene: Transcribed unprocessed pseudogene on chromosome 19 (12,092,468 to 12,113,048, forward strand). Ensembl gene ENSG00000214189.
Diseases named in the same sentence as ZNF788P in open-access papers:
ZNF788P is named in the same sentence as 3 diseases in open-access papers, as found by Europe PMC text mining. Sharing a sentence is not in itself a finding about the gene and the disease. The quoted sentences say what the papers report.
kidney failure (1 paper, 2022). An acute or chronic condition that is characterized by the inability of the kidneys to adequately filter the blood. "Methylation at cg17944885, located between genes ZNF788P and ZNF625-ZNF20, represented the strongest signal associated with the risk of kidney failure in individuals with macroalbuminuria (HR [95% CI] = 2.31[1.95, 2.76], p = 1.40 × 10−21)." (PMID 36550108, 2022).
ZNF788P also shares sentences with these, for which no sentence is quoted: leukemia (1 paper); tumor (1).